IL6 (interleukin 6)
Diseases named in the same sentence as IL6 in open-access papers (continued):
Sharing a sentence is not in itself a finding about the gene and the disease.
psoriasis (continued). "Repetitive doses of IP and etanercept applied to the surface of IMQ-induced psoriasis skin significantly reduced the expression levels of IL-6 mRNA by 50%." (PMID 35335900, 2022). "It is well known that in the pathogenesis of psoriasis, cytokines such as IL-1, IL-4, IL-6, IL-8, IL-12, and TNF are involved." (PMID 35269613, 2022). "The serum levels of pro-inflammatory cytokines such as IFN-7, TNF-α, IL-1β, IL-6, IL-8, and IL-17 significantly decreased in patients with psoriasis after a three-month administration of vitamin D supplement." (PMID 36558443, 2022). "IL-6 and IL-8 have been proven to play important roles in psoriasis, and both of them can initiate STAT3 and JNK MAPK pathway, thus involving in regulating cell inflammation and proliferation of keratinocytes." (PMID 35586566, 2022). "Cytokines such as tumor necrosis factor-alpha (TNFα) and interleukin 6 (IL-6) are directly involved in the pathology of psoriasis and are targets of some highly effective therapies." (PMID 35806402, 2022). "IL-6 is one of the most significant cytokines to be intensively elevated by DCs, Th17 cells and even keratinocytes during psoriasis flare, since it plays a major role in mediating inflammation." (PMID 35203707, 2022). "A recent study indicates that psoriasis-like inflammation damages the renal function via the TLR4-mediated IL-6 production in mice." (PMID 36382932, 2022). "Dysregulated inflammatory pathways and increased levels of proinflammatory cytokines, such as TNF-α, IL-6, and IL-8, are critical in the pathogenesis of psoriasis." (PMID 36110097, 2022). "Bifidobacterium infantis can reduce the ability of systemic pro-inflammatory biomarkers and make INF-α decreased in chronic fatigue syndrome and psoriasis, and IL-6 decreased in ulcerative colitis and chronic fatigue syndrome." (PMID 36250045, 2022). "In psoriasis, keratinocytes regulate differentiation and activation of Th17 and Th22 cells by producing IL-1β and IL-6." (PMID 35069008, 2022). "Connection between PRINS and psoriasis has been described in several earlier studies; for example, through the regulation of certain inflammatory mediators (IL-6 and CCL5) by PRINS in nucleic-acid-induced inflammatory reactions." (PMID 35008970, 2022). "Other proinflammatory cytokines, including IFN-γ, TNF-α, IL-1β, IL-6, IL-22, IL-26, IL-29, or IL-36, have also been reported to play important roles in the development of psoriasis." (PMID 35313642, 2022). "Inflammation-related factors such as TNF, IL6, and IL1β were abnormal throughout the pathogenesis of psoriasis." (PMID 35265149, 2022). "25-hydroxy vitamin D downregulates the expression and production of several pro-inflammatory cytokines including TNF-α, IL-1β, IL-6, and IL-8, thereby establishing its anti-inflammatory effect on the inflammatory profile of psoriasis." (PMID 36261848, 2022). "STAT3 conveys signals from psoriatic cytokines, such as IL-6, IL-17, IL-21, IL-22, and IL-23, to the nucleus and triggers an inflammatory response, which is involved in the pathogenesis of psoriasis." (PMID 35116069, 2022). "IL-23 is important for inducing IL-6-dependent epidermal hyperplasia and cytokine production in psoriasis." (PMID 34054833, 2021). "Important examples of such cytokines produced by keratinocytes in the skin of psoriasis patients are IL-6 and IL-8." (PMID 34641358, 2021). "Psoriasis patients exhibit enhanced circulating levels of IL-6, IL-18, IL-17A, IFN-γ, TNF, IL-1β, IL-27 and IL-29." (PMID 34068473, 2021). "In the animal model used in this study, the serum in IMQ-treated mouse showed an elevated level of M1-related cytokines (TNF-α, IL-6, IL-23) along with the decrease of the serum IL-10 level, which was accorded with human psoriasis." (PMID 33858431, 2021). "Most of these targets exhibited abnormal expression and were designated as the therapeutic targets in psoriasis, such as the cytokines and chemokines (IL-1β, IL-6, TNF, IFN-γ, CXCL8, CCL2)." (PMID 34168554, 2021).
psoriasis (continued). "Certain cytokines such as TNF-α, IL-17, IL-23, and IL-6 play a significant role in the pathogenesis of both psoriasis and uveitis." (PMID 33802255, 2021). "The results indicated that SHR168442 gave excellent efficacy in both preclinical mouse psoriasis models with favorable PK profile and significant suppression of signature cytokines, IL-17, TNFα and IL-6." (PMID 33911101, 2021). "In inflammatory processes, including psoriasis, IL-1Ra can inhibit inflammation by reducing granulocyte infiltration and releasing proteases, IL-6, and fibrinogen." (PMID 34360845, 2021). "These are the same pro-inflammatory cytokines that underlie the immune mechanisms of psoriasis, including TNF-alpha, IL-6, and C-reactive protein." (PMID 34441010, 2021). "IL-6, which is a critical cytokine for Th17 differentiation, inhibits Treg cells by inhibiting the expression of Foxp3 in psoriasis pathogenesis." (PMID 34975883, 2021). "In these cases, psoriasis-specific pro-inflammatory cytokines such as IL-1, IL-6, and TNF-alpha occur at much higher levels than usual in maternal serum or umbilical cord blood." (PMID 34441010, 2021). "This cytokine is released by keratinocytes and plays a main role in the pathogenesis of psoriasis since it stimulates the production of other pro-inflammatory cytokines such as IL-6." (PMID 34948364, 2021). "An example is psoriasis, of which transcriptome analysis determined that IL-6 is up-regulated 4.3-fold in psoriatic lesions." (PMID 33466954, 2021). "TNF-α increases the production of pro-inflammatory cytokines including IL-1 and IL-6, and activates the NF-κB-signaling pathway, which promotes the development of psoriasis." (PMID 34679744, 2021). "those of greatest clinical interest are IFN-γ, IL-6, IL-8, IL-12, whose serum levels are systematically increased in serum of psoriasis patients." (PMID 34829740, 2021). "S100A7 and HBD-2, known as antimicrobial peptides, are related to innate and adaptive immunity, and IL-6 affects keratinocyte proliferation in psoriasis." (PMID 34445513, 2021). "Clinically, IL-6 targeted blockade are ineffective or even detrimental in psoriasis and other indications." (PMID 34215755, 2021). "IL-6 and IL-8 play a central role in the pathogenesis of psoriasis, because they activate lymphocytes in psoriatic inflammation." (PMID 33801280, 2021). "Consistent with the perturbed TNF/IL-12/IL-6 secretion, we found that Zc3h12c−/− mice had ~2-fold lower murine Psoriasis Severity Index (mPASI) score than Zc3h12c+/+ mice at days 3–4, the peak of IMQ-induced psoriatic lesions." (PMID 34215755, 2021). "Tape stripping together with the stimulation with psoriasis cytokines increased IL-6 expression compared to biopsies treated only with cytokines or tape stripping." (PMID 33801280, 2021). "A total of 389 significant genes were common to both hepatitis C and psoriasis, which mainly involved IL6, TNF, IL10, ALB, STAT3 and CXCL8." (PMID 34215260, 2021). "The inflammatory factors IL6 and CCL2 (encoding MCP1 protein) were highly overexpressed as a result of the combined psoriasis-induction stimuli that reflects acute inflammation changes." (PMID 33986690, 2021). "The success of the monoclonal antibody tocilizumab targeting IL-6 in palmoplantar pustular psoriasis and psoriatic arthritis has been overshadowed by the exacerbation of psoriasis in some of the treated patients." (PMID 34641358, 2021). "Potent pro-inflammatory cytokines such as TNF-α and IL–6 are capable of inducing proliferation activities and play a major role in the pathogenesis of psoriasis." (PMID 34947782, 2021). "Macrophages are largely infiltrated in the dermal layer of psoriasis to release cytokines IL-23, IL-6, and TNF-α during the development of the lesion." (PMID 34054833, 2021).
psoriasis (continued). "She consulted the rheumatology department for consideration of 30 mg/day PSL, but was bio-switched to the IL-6 inhibitor sarilumab (SAR) in June Y+2 due to the high risk of infection and a history of synovitis and psoriasis induced by TNF inhibitors." (PMID 35008766, 2021). "Among them, serum IL-6 and IL-22 levels were considered to be positively correlated with the severity of psoriasis inpatients." (PMID 33685393, 2021). "In psoriasis, IL–6 production is increased, which synergizes TNF-α and IL–1 to advance the hyperproliferation of epidermis by its activity on epidermal growth factor receptor." (PMID 34947782, 2021). "Psoriasis leads to an immune-mediated increase in multiple proinflammatory cytokines, including IL-1 and IL-6." (PMID 34828770, 2021). "IL-6 is elevated in skin inflammation such as psoriasis, atopic dermatitis, and allergic contact dermatitis, but also associated with skin healing." (PMID 34086734, 2021). "The effect of HL, HP and CA on the release of pro-inflammatory cytokines like IL-6 and IL-8 was studied in our ex vivo psoriasis model." (PMID 33801280, 2021). "On the other hand, biological agents targeting TNF, IL-23 and IL-17 have shown promising efficacy during the clinical treatment of psoriasis, while IL-6 inhibitors, IL-21 inhibitors and recombinant human IL-10 treatment didn’t attain the results as expected." (PMID 34975883, 2021). "The molecule that primarily establishes a difference between patients with new-onset psoriasis and healthy subjects is IL-6." (PMID 34006909, 2021). "Galectin-7 was found to play a role in the pathogenesis of psoriasis, an inflammatory process affecting stratified squamous cells of the skin by elevating levels of IL-6 and IL-8." (PMID 34638303, 2021). "Topical application of SHR168442 in Vaseline exhibited excellent efficacy in the imiquimod-induced and IL-23-induced psoriasis-like skin inflammation mouse models and correlated with the reduction of Th17 pathway cytokines, IL-6, TNFα and IL-17A." (PMID 33911101, 2021). "IL-23, having a crucial role in psoriasis initiation, is capable of evoking IL-6-dependent cytokine release and epidermal thickening." (PMID 34638757, 2021). "To imitate the excessive IL-6 production by pDCs in MCPIP-deficient inflamed skin, we injected WT mice skin with recombinant IL-6 at the beginning of IMQ-induced psoriasis model." (PMID 34215755, 2021). "Serum IL-17A, IL-22, and IL-6 concentrations were significantly higher in psoriasis patients compared with the control group." (PMID 33171607, 2020). "Previous findings demonstrate an increased expression of tumor necrosis factor (TNF)-α, nuclear factor-kappa B, IL-6, and IL-8 in psoriasis-affected nails." (PMID 32759698, 2020). "In psoriasis skin biopsies, the synthesis of proinflammatory cytokines, including IL-1β, IL-6, and TNF-α, was significantly enhanced by TCDD and chloroquine, compared to controls." (PMID 32235789, 2020). "Increased levels of serum ACE, IL-6 and IL-8 in psoriasis patients were due to the important role of ACE in inflammation." (PMID 31914957, 2020). "The baseline serum levels of psoriasis-related cytokines (IL-6, IL-17A, and IL-23A) were the same between WT and PD-1−/− mice (n = 3)." (PMID 33060784, 2020). "IL-6 promotes Th17 cell differentiation and keratinocyte proliferation, but, interestingly, anti–IL-6 treatment has been shown to be ineffective for psoriasis." (PMID 33055429, 2020). "Collectively, IL-6 expression related to expression of Th17 cytokines and infiltration of neutrophils correlates with PD-1 deficiency-enhanced IMQ-induced psoriasis-like dermatitis." (PMID 33060784, 2020). "It has been shown that a change in the relative abundance of commensurate skin bacteria and an imbalance of Th1 and Th2 activities with upregulated inflammatory mediators such as IL-6 and IL-17 worsened the inflamed skin of AD and psoriasis." (PMID 31979095, 2020).
psoriasis (continued). "The mice showed dermal expression of IFN-γ, IL-6, IL-17, IL-22, IL-23, and IL-36 in the skin, which is an inflammatory pattern typical for psoriasis." (PMID 33643287, 2020). "Microvascular abnormalities related to endothelium activation, such as in psoriasis or CVD can result in endothelial cytokine release including IL-6 that can circulate into the marrow and affect erythropoiesis." (PMID 31936662, 2020). "LL-37 stimulate mDCs to secrete TNF-α and IL-6, and mDCs are able to activate naïve-T cells and induce their polarization to Th1/Th17 cells in psoriasis." (PMID 32509872, 2020). "IL-6 is expressed by human keratinocytes and is reported to be overexpressed in many inflammatory skin diseases, such as psoriasis, CLE, and lichen planus." (PMID 33055429, 2020). "IL-6 is required for IL-22-mediated skin inflammation and epidermal hyperplasia in psoriasis by regulating the expression of IL-22 receptor chain IL-22R1." (PMID 33149756, 2020). "For instance, high level IL-6 in wounded tissue has been reported as required for the dampened regulatory T cell activity detected in psoriasis patients." (PMID 32993791, 2020). "In summary, IL-6 plays important roles during disease development of PD-1 signal blockade-induced psoriasis-like dermatitis." (PMID 33060784, 2020). "The increase of serum IL-6 levels post-treatment with anti-PD-1 blocking antibody implies that the pathogenesis of PD-1 signal blockade-induced psoriasis-like dermatitis is dependent on IL-6." (PMID 33060784, 2020). "In other autoimmune disorders such as psoriasis, IL6 signaling prevents immune suppression by Tregs." (PMID 33101305, 2020). "Chloroquine or TCDD treatment of psoriasis skin biopsies enhanced the production of the proinflammatory cytokines, IL-1β, IL-6, and TNF-α compared to chloroquine- or TCDD- treated controls." (PMID 32235789, 2020). "In vivo studies suggested the topical application of TRA and BT dual-loaded liposomal gel had the best ability to reduce the thickness of epidermal and the level of cytokines (TNF-α and IL-6), largely alleviating the symptoms of psoriasis." (PMID 32448273, 2020). "Our observations on human samples indicated enhanced epidermal infiltration of CD8 T cells, and the pathogenesis of which appears to be dependent on IL-6 in the PD-1 signal blockade-induced psoriasis-like dermatitis." (PMID 33060784, 2020). "IL-6 is significantly up-regulated during psoriasis and it is known that keratinocytes as well as monocytes and neutrophils produce IL-6 during psoriatic inflammation." (PMID 33643287, 2020). "qRT-PCR analysis revealed that unstimulated ear skin from PD-1−/− and WT mice contain similar low levels of psoriasis-related cytokines, IL-6, IL23-A, and IL-17A (P = 0.95, P = 0.57 and P = 0.21 by Mann–Whitney U test, respectively)." (PMID 33060784, 2020). "It was reported that the serum levels of IL-8 and IL-6 were significantly higher in psoriasis patients compared to healthy subjects." (PMID 31660855, 2019). "Apart from TNF-α, interleukin-6 (IL-6), interleukin-12 (IL-12) and interleukin-23 (IL-23) are also involved in the pathogenesis and clinical manifestations of psoriasis." (PMID 31291937, 2019). "For example, psoriasis-like skin inflammation induced by intradermal injection of recombinant IL-23 is abrogated in IL-6 knockout mice." (PMID 31659208, 2019). "Th17 cells are major players in imiquimod-induced psoriasis as well, and pDCs have been reported to secrete pro-Th17 cytokines (e.g., IL-6) in response to TLR7 ligation." (PMID 31105556, 2019). "IR is strongly influenced by the activity of pro-inflammatory adipocytokines, as TNF-α, IL-6, and leptin, inducing a state of persistent low-grade inflammation that underlies the physiopathology of both NAFLD and psoriasis." (PMID 31540048, 2019). "In the present study, IL-6, IL-12p40, and IL-23 mRNA were shown to be over-expressed, and the levels of these cytokines were also increased in the psoriasis group." (PMID 31291937, 2019).
psoriasis (continued). "For instance, it antagonizes the activation of signal transducer and activator of transcription 3 (STAT3) and the subsequent production of IL-6, which is a major inflammatory molecule involved in psoriasis." (PMID 30918469, 2019). "We observed that CAV-1-reduced monocytes exacerbated the production of psoriasis-related inflammatory cytokines (IL-1β and IL-6)." (PMID 30644419, 2019). "ERK phosphorylation can also activate Th17 cells and then promote the secretion of inflammatory cytokines TNF-α, IL-6, and IL-17A, which positively correlate with psoriasis." (PMID 31824416, 2019). "The immunohistochemical analysis was directed to the immunoreactivity of antibodies anti-IL-6, anti-IL-17, and anti-IL-23 in both GT and psoriasis." (PMID 31789253, 2019). "The production of pro-inflammatory cytokines TNF-α, IL-6, IL-12p40, and IL-23 of the hPBMCs from the psoriasis patients were significantly higher than that of the healthy subjects (P < 0.001)." (PMID 31291937, 2019). "In conclusion, TNF-α, IL-6 and IL-1β are increased in psoriasis and correlate with PASI scores and obesity, leading to worsening of psoriatic lesions." (PMID 31521168, 2019). "There is evidence supporting the beneficial effects of IL-6 inhibition in the treatment of psoriasis." (PMID 31659208, 2019). "The immunostaining of the three antibodies (anti-IL-6, anti-IL-17, and anti-IL-23) presented a similar cytoplasmic staining pattern, predominantly basal and parabasal, in both GT and psoriasis." (PMID 31789253, 2019). "The aim of this study was to investigate and compare inflammatory responses and the Th17 pathway through evolution of the expression of IL-6, IL-17, and IL-23 in psoriasis and GT." (PMID 31789253, 2019). "The inflammatory process and immunostaining of IL-6, IL-17, and IL-23 were similar in geographic tongue and psoriasis, suggesting the existence of a type of geographic tongue that represents an oral manifestation of psoriasis." (PMID 31789253, 2019). "IL-6 is another important cytokine released by the mast cells and the role of IL-6 has also been well documented in the pathogenesis of psoriasis." (PMID 31710084, 2019). "The mRNA expression levels of TNF-α, IL-6, IL-12p40 and IL-23 genes in hPBMCs obtained from psoriasis patients were significantly higher than that from healthy control (30.22, 7.5, 6.8 and 22.4 fold, respectively, P < 0.001)." (PMID 31291937, 2019). "Among these cytokines, IL-6 has been reported to be present at high levels in psoriatic skin and in the plasma of psoriasis patients, suggesting its critical role in psoriasis." (PMID 31659208, 2019). "Blocking the release of IL6 from the epidermis of psoriasis patients inhibits IL23-induced IL17 production." (PMID 31861934, 2019). "Both naringin and sericin alone significantly decreased the expression of mRNA and the production of TNF-α, IL-6, IL-23, and IL-12p40 by hPBMCs from psoriasis patients, with similar potency of activity." (PMID 31291937, 2019). "Let-7b directly targets IL-6, an essential cytokine regulating cell differentiation, which has been shown to be induced in the epidermis of lesioned skin from psoriasis patients." (PMID 30219085, 2018). "Top up-regulated DEGs in CP vs C include previously identified psoriasis-associated genes such as IL36A/G, SPRR2A/B/F, SERPINB4, S100A7A, S100A9, and IL17F while top down-regulated DEGs include SERTM1, IL6, and ADAMTS16." (PMID 30054515, 2018). "Serum levels of TNF-α, IFN-γ, IL-2, IL-6, IL-8, IL-18, IL-22, chemerin, lipocalin-2, resistin, sE-selectin, fibrinogen, complement 3, and adiponectin correlate with psoriasis and can be used as potential biomarkers for psoriasis and response to the treatment." (PMID 29416693, 2018). "Multiple cytokine signaling pathways involved in the pathogenesis of psoriasis, including IL-1, IL-6, IL-17A and interferon signaling, were enriched in the current analysis." (PMID 29871627, 2018).